HM13 (histocompatibility minor 13)
Diseases named in the same sentence as HM13 in open-access papers (continued):
Sharing a sentence is not in itself a finding about the gene and the disease.
tumor (20 papers, 2015 to 2026). "Strikingly, HM13 overexpression was clearly associated with tumor stage, and even—upon adjustment for sex and age—with survival." (PMID 39199324, 2024). "Purity analysis showed that HM13 expression also showed a marked association with the tumor purity in SARC, UVM, KIRC, GBM, UCS, and LGG." (PMID 36046831, 2022). "Analysis of expression of imprinted genes in the pancancer data confirmed the association of increased expression of two genes, BLCAP and HM13, at 20q11-q13.32 with tumor cell resistance to multiple agents." (PMID 36461044, 2022). "Moreover, we elucidated the potential mechanism underlying HM13 action in tumor development and genesis and identified the correlation of HM13 expression with tumor mutation load, immune cell invasion, microsatellite instability, and tumor purity in the tumor microenvironment." (PMID 36046831, 2022). "However, the expression of HM13 and its prognostic value, association with tumor-infiltrating immune cells (TIICs) in the microenvironment, and potential to predict immunotherapeutic response in HCC are unknown." (PMID 35964022, 2022). "Strikingly, HM13 expression increased as the tumor progressed throughout clinical stages (p = 2.90 × 10−8)." (PMID 39199324, 2024). "The relationship between HM13 expression and tumor progression was explored and the results revealed that both HM13 mRNA (p < 0.05) and protein expression (p < 0.05) significantly increased in later stages of HCC compared with that in early stages." (PMID 35964022, 2022). "In vivo, a high expression level of HM13 was correlated with a large tumor size and a high tumor weight." (PMID 36153332, 2022). "Subsequently, we analyzed the protein expression of HM13 between normal and HCC tumor tissues, and significant HM13 overexpression was observed in HCC tumor tissues." (PMID 36046831, 2022). "As well, a higher expression level of HM13 was observed in high tumor stages compared to low tumor stages." (PMID 36046831, 2022). "Through immune checkpoint gene expression analysis, the expression of HM13 was found to exhibit a significant correlation with several tumor inhibitory genes, especially VEGFB, LAG3, CD274, and TGFB1." (PMID 36046831, 2022). "Methylation of probe cg18471488 was significantly correlated with expression of the last exon of transcript 4 (possibly the UTR of this transcript) but also the full HM13 gene in the whole dataset (control and tumour data)." (PMID 30297886, 2018). "HM13, on the other hand, was significantly upregulated in biallelically expressing samples (compared to monoallelically expressing tumours as well as monoallelically expressing controls), further confirming the results presented above." (PMID 30297886, 2018). "Moreover, HM13 overexpression consistently exacerbated with increasing tumor stage (p = 2.90 × 10−8)." (PMID 39199324, 2024). "ROC analysis showed that the expression of HM13 could differentiate tumor tissues from normal tissues to a certain extent, and the AUC was 0.962." (PMID 36046831, 2022). "In addition, the analysis from GEO datasets also indicated that HCC tissues highly expressed HM13, while it was poorly expressed in the non-tumor tissues." (PMID 36046831, 2022). "Currently, very little research has disclosed how HM13 plays a role in tumor development." (PMID 36046831, 2022). "The results showed a higher HM13 expression in HCC tumor tissues." (PMID 36046831, 2022). "Differential analysis indicated significant overexpression of HM13 in HCC tumor tissues." (PMID 36046831, 2022). "HM13 expression was abnormal and up-regulated in several tumor tissues." (PMID 36046831, 2022). "Similarly, HM13 expression tended to be high in all tumor types." (PMID 36046831, 2022). "In addition, the enrichment analysis showed that HM13 may act as effective parameters in regulating tumor metabolism." (PMID 36046831, 2022).
tumor (continued). "Therefore, our findings suggested that HM13 was crucial for tumor genesis and development, and could be used as a marker for tumor diagnosis and prognostic evaluation." (PMID 36046831, 2022). "Therefore, we reasonably speculated that the expression of HM13 could promote the interaction between tumor and immune cells, which provides a new indicator for monitoring immunotherapy or a new adjuvant therapeutic target." (PMID 36046831, 2022). "When taking into account the different tumour subtypes, we detected 24 SNPs (in eight genes: ZDBF2, PEG10, MEST, H19, IGF2, MEG3, ZNF331 and HM13) exhibiting DI in at least one subtype compared to the normal tissue samples." (PMID 30297886, 2018). "For HM13, we verified that overexpression was (at least partially) driven by differential imprinting by first identifying LOI samples (see Section 2) and subsequently comparing the expression of LOI tumor with non-LOI tumor and matched solid tissue normal samples." (PMID 39199324, 2024).
HM13 also shares sentences with these, for which no sentence is quoted: infection (10 papers); glioblastoma (5); Alzheimer disease (4); malaria (4); lung adenocarcinoma (3); endometrial cancer (2); Insulin resistance (2); latent infection (2); ocular infection (2); prostate carcinoma (2); acute myeloid leukaemia (1); adrenocortical carcinoma (1); Autoimmunity (1); Blindness (1); breast invasive carcinoma (1); chronic hepatitis C (1); Clear Cell Renal Cell Carcinoma (1); colon adenocarcinoma (1); congenital hydronephrosis (1); corneal infection (1); cutaneous melanoma (1); diabetes (1); Ebola virus disease (1); endometrium carcinoma (1); esophageal carcinoma (1); Granuloma (1); head and neck squamous cell carcinoma (1); hepatic diseases (1); Hepatitis (1); hepatitis C (1).
A further 15 diseases each share a sentence with HM13 in 1 paper.